CD4 (CD4 molecule)
Diseases named in the same sentence as CD4 in open-access papers (continued):
Sharing a sentence is not in itself a finding about the gene and the disease.
foot and mouth disease (2 papers, 2020 to 2025). A viral infectious disease that results in infection in cattle and swine, has material basis in foot-and-mouth disease virus, which is transmitted by contaminated fomites, or transmitted by ingestion of food contaminated with infected meat or animal products. "It has been speculated that the CD4+/CD8b+ T cell population may be an uncharacterized population of peripheral T helper cells, as an increase in CD4+/CD8+ T cells was observed in accordance with B cell proliferation following vaccination for foot and mouth disease in cattle." (PMID 40316897, 2025).
frontotemporal dementia (2 papers, 2022 to 2024). Frontotemporal dementia (FTD) comprises a group of neurodegenerative disorders, characterized by progressive changes in behavior, executive dysfunction and language impairment, as a result of degeneration of the medial prefrontal and frontoinsular cortices. "Of the inflammatory proteins assessed in the brain, five chemokines were upregulated in Pick’s disease cases (P < 0.0400), consistent with the recruitment of CD4+ (P = 0.0109) and CD8+ (P = 0.0014) T cells." (PMID 37703311, 2024).
functional dyspepsia (2 papers, 2020 to 2021). "Association between patients and controls based on the existence of CD4 and CD8: For the investigation of association between disease and the presence of T cells, first we compared functional dyspepsia patients and healthy individuals based on CD4+ and CD8+ T-cell counts in gastric mucosa." (PMID 32509242, 2020). "However, further studies involving larger sample size or describing effective factors should be performed to validate the relationship between CD4+ and CD8+ T cells, interfering factors and increased risk of functional dyspepsia." (PMID 32509242, 2020). "As there is a significant difference between patients and control regarding the presence of CD4 and CD8, it could be concluded that CD4 and CD8 have a protective role in functional dyspepsia." (PMID 32509242, 2020). "The results of this study suggest that the absence of CD4+ and CD8+ T cells may be associated with increased risk of functional dyspepsia." (PMID 32509242, 2020). "In conclusion we aimed to measure T-lymphocyte-type CD4+ and CD8+ as indicators of the immune system in patients with Helicobacter pylori-negative functional dyspepsia." (PMID 32509242, 2020). "The aim of this study was to investigate and compare CD4+ and CD8+ in the Helicobacter pylori-negative functional dyspepsia and control groups." (PMID 32509242, 2020).
gallbladder adenocarcinoma (2 papers, 2003 to 2021). A carcinoma that arises from glandular epithelial cells of the gall bladder. "To validate the scRNA‐seq results, we analyzed independent gallbladder adenocarcinoma and adjacent normal tissues by immunohistochemistry (IHC) staining and found a significant increase of FOXP3+ or CD4+ cells and a reduction of CD8A+ cells in tumors." (PMID 34185421, 2021). "We sought to determine the relationship of the intratumoural infiltration of CD4+ T cells, CD8+ T cells, NKCs, and DCs with tumour progression to identify favourable prognostic factors for patients with adenocarcinoma of the gallbladder." (PMID 14583778, 2003). "Though the prognosis associated with TILs is not always good, CD4+ and CD8+ TILs and intratumoural DC infiltration, rather than NKCs, correlate with tumour progression, possibly serving as good prognostic predictors in patients with adenocarcinoma of the gallbladder." (PMID 14583778, 2003). "In this study, we demonstrate that CD4+ and CD8+ tumour-infiltrating lymphocyte and DCs, but not NKCs, are important factors in the accurate prognosis of survival after surgical removal of gallbladder adenocarcinoma." (PMID 14583778, 2003).
gallstones (2 papers, 2009 to 2025). Solid crystalline precipitates in the biliary tract, usually formed in the gallbladder, resulting in the condition of cholelithiasis. "In our study, the study group exhibited significantly higher CD3+, CD4+, CD8+, and CD4+/CD8+ levels compared to the control group (P < 0.05), affirming the beneficial impact of early enteral nutrition on immune function following gallstone surgery." (PMID 39937806, 2025).
gastric MALT lymphoma (2 papers, 2019 to 2024). "In their study, CagY-specific CD4 + clones from patients with gastric MALT lymphoma promoted the proliferation of B cells by producing IFN-γ and IL-17 (produced by T helper 17 [Th17] cells)." (PMID 39558403, 2024). "Most of the tumor-infiltrating CD4+ cells in gastric MALT lymphoma were shown to be FOXP3+ Tregs, and these Tregs were recruited by tumor cells through the chemokines CCL17 and CCL22, secreted by FOXP3+ Tregs." (PMID 30999581, 2019). "In the murine model of Helicobacter felis (H. felis)-induced gastric MALT lymphoma, tumor-infiltrating CD4+ T cells co-express surface markers CD28 and CD69, and produce large quantities of IL-4, but not of interferon-gamma (INF-γ)." (PMID 30999581, 2019). "In addition to classic T-cell mechanisms, previous studies have shown that self-antigen-stimulating B-cell receptor signaling and CD4+CD25+Foxp3+ regulatory T cell-originated signals participate in the pathogenesis of gastric MALT lymphoma." (PMID 39558403, 2024).
gastrointestinal stromal tumor (2 papers, 2012 to 2024). "In gastrointestinal stromal tumors, the expression of ANO1 was significantly negatively correlated with infiltration of plasma cells and memory-activating CD4-positive T cells, suggesting that ANO1 may be participate in the functional suppression of T cells." (PMID 38352864, 2024). "This was achieved by analyzing the expression of CD3+, CD4+, CD8+ and CD20+ lymphocytes in the peritumoral capsule from 80 patients with non-gastrointestinal stromal tumors (non-GIST) STS, in relation to other clinico-pathological variables." (PMID 22375962, 2012).
generalized anxiety disorder (2 papers, 2022 to 2023). An anxiety disorder characterized by excessive and difficult-to-control worry about a number of life situations. "One study that examined a mixed group of patients with either generalized anxiety disorder or panic disorder showed a lower CD4 + /CD8 + T cell ratio in blood leukocytes compared to healthy volunteers, which was due to an absolute increase in the number of CD8 + T cells in patients." (PMID 35092543, 2022). "By FDR correction (PFDR<0.05), we found two immunophenotypes to be protective against generalized anxiety disorder: CD24+CD27+B cells and CD28+CD4+T cells." (PMID 38264647, 2023).
germinoma (2 papers, 2018 to 2025). A malignant germ cell tumor arising in the central nervous system. "Lastly, in germinomas, the proportion of CD4+ Th cells exceeded that of CD8+ Tc cells, possibly indicating that cytotoxic T cells are not fully functional, leading to poor tumor control." (PMID 39958339, 2025). "In germinomas, CD3+ and Foxp3+ cells strongly correlated with CTLA-4 expression (p<0.001), and CD4+, CD8+, and Foxp3+ cells with PD-1 expression (p<0.05)." (PMID 39958339, 2025). "This study examined expressions of PD-1 and PD-L1 in intracranial germinoma and characterized the subtypes of TILs showing surface antigens such as CD3+, CD8+, CD4+, and Foxp3+ using a quantitative evaluation method." (PMID 29617441, 2018). "The study revealed that germinomas exhibited significantly higher infiltration of CD4+ and Foxp3+ T cells compared to non-germinomatous GCTs (NGGCTs)." (PMID 39958339, 2025). "In germinomas, CD3+, CD4+, CD8+, and Foxp3+ cells infiltrated at 13.49% (range: 0.40%-40.91%), 6.44% (range: 0.37%-15.39%), 4.69% (range: 0.37%-16.99%), and 1.75% (range: 0.06%-7.76%), respectively, with CD4+ T cell levels being significantly higher than CD8+ cells (p=0.010, data not shown)." (PMID 39958339, 2025).
gestational diabetes mellitus (2 papers, 2022 to 2024). "An analysis of the blood of patients with gestational diabetes mellitus (GDM) has demonstrated reduced CD4+CD25+ Treg cell numbers and increased pro-inflammatory cytokines IL-6 and TNF-a." (PMID 38732104, 2024). "Recently, we investigated the modulation of immune cell frequencies in gestational diabetes, and found that gestational diabetes mellitus (GDM) modulated the frequencies of total CD3+ and CD4+ T and B cells, suggesting that immune cells could play specific role in the prognosis of this disease." (PMID 36992781, 2022).
glomerular diseases (2 papers, 2018 to 2021). "No statistical difference was found between the three glomerulopathies in the absolute count of FOXP3+ Tregs in the interstitial tissue per mm2 and FOXP3+ Tregs over CD4+ and CD3+ ratios." (PMID 34336285, 2021).
gynecologic cancer (2 papers, 2024). "Consistent with the findings of previous studies, our results showed that CD8+/CD4+ T cell ratio increased continuously post-infusion, and higher relative CD8+/CD4+ T cell ratio contributed to survival benefit in patients with gynecologic cancer." (PMID 38769543, 2024).
Gynecomastia (2 papers, 2017 to 2019). Abnormal development of large mammary glands in males resulting in breast enlargement. "Among those that developed gynecomastia, the median baseline CD4 count was 318 cells/mm3 (IQR: 192–467) while the median baseline BMI was 21 kg/m2 (IQR: 19–23)." (PMID 31409277, 2019).
hairy cell leukemia (2 papers, 2022 to 2023). Hairy cell leukemia (HCL) is a rare type of leukemia in which abnormal B-lymphocytes are present in the bone marrow, spleen and peripheral blood. "In classical hairy cell leukemia (HCL), standard treatments including purine analogs achieve a durable response (up to 90%), but lead to severe immunosuppression and long-lasting depletion of CD4 + T lymphocytes." (PMID 36494600, 2023).
Hand-foot syndrome (2 papers, 2024). "Clinical efficacy, disease control rate (DCR), survival time (ST), immune indicators (CD3+, CD4+, CD4+/CD8+), and adverse reactions (ARs) (including mild fatigue, liver pain, hand-foot syndrome (HFS), diarrhea, and fever) were compared for patients in different groups after different treatments." (PMID 38605359, 2024).
hemangioma (2 papers, 2013 to 2021). A benign vascular lesion characterized by the formation of capillary-sized or cavernous vascular channels. "Notably, the frequency of IL-17+ CD4+ cells exposed to CM was increased both in HCC patients (from 2.03 ± 0.23% to 9.04 ± 0.52%, P < 0.01) and in hemangiomas patients (from 1.96 ± 0.25% to 7.02 ± 0.37%, P < 0.01)." (PMID 23305119, 2013).
hemorrhagic cystitis (2 papers, 2019 to 2024). Inflammation of the bladder resulting in bloody urine. "In case of cellular products manufactured by a different method, such as AlloVir® T-cell treatment (Viralym-M), it was clearly demonstrated that CD4+ T-cell subpopulation was of importance for the treatment of BK virus hemorrhagic cystitis." (PMID 37414968, 2024). "BKPyV-specific CD4+ and CD8+ T cell recovery were associated with successful BKPyV clearance in pediatric HSCT recipients with a diagnosis of BKPyV-associated hemorrhagic cystitis." (PMID 31744480, 2019).
Hepatic cysts (2 papers, 2015 to 2022). "Therefore, local CD4+ T-cell predominance favored the establishment of hepatic cysts between 4 and 6 weeks." (PMID 36046744, 2022). "T cells dominated by the CD3+ subtype reported in the pericystic adventitia of the hepatic cysts in sheep, while CD8+ and CD4+ cells were the most frequent populations in cattle with progressive and regressive cysts, respectively." (PMID 26578348, 2015).
hepatitis D (2 papers, 2024 to 2025). "Determinants of HBV DNA >2000 IU/mL while people were off tenofovir were detectable HIV RNA (p = 0.041), lower CD4+ T-cell count (p = 0.027), HBeAg positive serology (p = 0.004) and positive hepatitis D serology (p = 0.001)." (PMID 39981332, 2024).
HIV-associated neurocognitive disorder (2 papers, 2012 to 2023). HIV-associated neurocognitive disorder (HAND) remains a common complication of HIV infection in the combination antiretroviral therapy (ART) era. "HLA-DR*04 was identified as a predictor of HIV-Associated neurocognitive disorder (HAND), low CD4 T-cell responses to HIV, and low plasma HIV RNA levels in a U.S. cohort." (PMID 22693541, 2012).
hypersomnia (2 papers, 2022). A sleep disorder characterized by excessive sleepiness. "More attention should be paid when patients exhibit hypersomnia, convulsions, stiff neck, vomiting, limb shaking, hyperarousal, fever, breathlessness and certain laboratory parameters (IL-6 levels, CD4+ levels, neutrophil ratio and lymphocyte ratio) which could reduce the intensification of HFMD." (PMID 35482791, 2022).
idiopathic nephrotic syndrome (2 papers, 2018 to 2021). Nephrotic syndrome for which no cause has been identified. "Purified CD4+CD25+ Tregs transfer to rats with an idiopathic nephrotic syndrome model resulted in significant proteinuria reduction." (PMID 34336285, 2021). "Most recently, low-dose IL-2 has also been shown to expand or modify CD4+ regulatory T cells in vitro from patients with SLE and children with the drug-resistant idiopathic nephrotic syndrome." (PMID 29619880, 2018).
idiopathic pneumonia syndrome (2 papers, 2013 to 2023). "This cell-intrinsic IDO1-AHR pathway represses STAT1-mediated IL6 expression and subsequently prevents CD4+ T cells from differentiating into pathogenic Th17 cells, which are a major effector responsible for idiopathic pneumonia syndrome (IPS)." (PMID 37394584, 2023). "In contrast, wild-type donor CD4+ T-cells mediated minimal inflammation, and CD8+ T-cells played a minor role in idiopathic pneumonia syndrome (IPS) development." (PMID 23843069, 2013).
ileus (2 papers, 2014 to 2024). Decrease in peristalsis in the absence of a mechanical bowel obstruction. "Here we report that a massive and rapid egress of monocytes and CD4+T cells from the spleen occurs during postoperative ileus but that contrarily to other acute inflammation models, these cells do not participate to the intestinal inflammation." (PMID 25010202, 2014).
Impaired glucose tolerance (2 papers, 2019 to 2022). An abnormal resistance to glucose, i.e., a reduction in the ability to maintain glucose levels in the blood stream within normal limits following oral or intravenous administration of glucose. "Children with impaired glucose tolerance and T1D exhibit a higher frequency of CXCR5+PD-1+ICOS+, CD4+CXCR5+, and CD4+CXCR5+ICOS+ circulating follicular helper T cells (Tfh)." (PMID 36704045, 2022).
inflammatory breast carcinoma (2 papers, 2019 to 2022). An advanced, invasive breast adenocarcinoma characterized by the presence of distinct changes in the overlying skin. "Similarly, in inflammatory breast cancer, low levels of peripheral blood CD8+ and CD4+ T lymphocytes associate with inferior survival." (PMID 35626676, 2022). "Herein, we aimed to identify the immunomodulatory role of tumor Syndecan-1 (CD138) in the polarization of CD4+ T helper (Th) subsets isolated from the tumor microenvironment of inflammatory breast cancer (IBC) and non-IBC patients." (PMID 31145753, 2019).
intervertebral disc degeneration (2 papers, 2025). "Bioinformatics analyses further reveal associations between Adam8 and immune cell populations, including CD8+ T cells and resting memory CD4+ T cells, as well as its involvement in intervertebral disc degeneration." (PMID 41008561, 2025).
intracranial aneurysm (2 papers, 2017 to 2025). "Numbers of positively stained saccular intracranial aneurysm (sIA) samples and mean, median, and range of leukocyte densities in CD3+, CD4+, CD8+, CD20+, CD68+, and CD163+ stainings." (PMID 40498464, 2025).
Japanese encephalitis (2 papers, 2016 to 2018). A disease due to a virus transmitted by an arthropod). "Furthermore, CD4 T cell release of IFN-γ may have an impact on disease outcome since CD4 T cells, and not CD8 T cells, were shown to dominate the IFN-γ response in recovered Japanese encephalitis (JE) patients." (PMID 30319632, 2018).
keratoacanthoma (2 papers, 2014 to 2023). A dome-shaped, rapidly growing skin lesion composed of well differentiated squamous cells. "In a study comparing T-lymphocyte profiles between keratoacanthomas (KA) and invasive human cSCC, CD8+ cells were found to be increased, whereas CD4+ cells were found to be decreased in cSCC relative to KA." (PMID 36980718, 2023).
Langerhans cell histiocytosis (2 papers, 2015 to 2021). Langerhans cell histiocytosis (LCH) is a systemic disease associated with the proliferation and accumulation (usually in granulomas) of Langerhans cells in various tissues. "ATL is a T cell lymphoproliferative tumor of mature CD4+ CD25 + T cells, and Langerhans cell histiocytosis is characterized by the accumulation of Langerhans cells and antigen-presenting cells." (PMID 34868263, 2021).
Langerhans cell sarcoma (2 papers, 2012 to 2019). A neoplastic proliferation of Langerhans cells with overtly malignant cytologic features. "T cell lineage markers except for CD4 in Langerhans cell sarcoma have not been documented previously." (PMID 23006414, 2012).
Lassa virus infection (2 papers, 2021 to 2025). "Mice expressing human HLA-A2 had high levels of viral replication and liver immunopathology after Lassa virus infection that was reduced after depletion of CD4 and CD8 T cells." (PMID 33400715, 2021). "In animals depleted for either CD4+ or CD8+ T cells, Lassa virus infection remained uniformly lethal, with only a slight delay in disease progression was observed in the CD4-depleted group when compared with nondepleted controls." (PMID 40996813, 2025). "Here, we assessed the role of CD4+ and CD8+ T cells on disease progression and severity of Lassa virus infection in a nonhuman primate model." (PMID 40996813, 2025).
Left ventricular dilatation (2 papers, 2019 to 2021). Enlargement of the chamber of the left heart ventricle. "The aortic root size was related with left ventricular dilation, decreased CD4+ T-cell count and elevated viral load." (PMID 31429736, 2019). "However, eliminating CD4+ T cells from the fourth week after ligation reduced the infiltration of CD4+ T cells in hearts and rescued the left ventricular dilatation in HF mice." (PMID 34630414, 2021).
lobomycosis (2 papers, 2019). A chronic, fungal, subcutaneous infection endemic in rural regions in South America and Central America. "Similarly, in human lobomycosis, there is dense, granulomatous inflammation with infiltration of macrophages, CD4+ T cells, multinucleated giant cells, and viable yeast cells." (PMID 31231361, 2019). "In addition, the proportion of CD4+ cells over the sum of CD2+ T lymphocytes and CD19+ B lymphocytes in “normal” dolphins was also 30% in a field study to quantify the immune changes in bottlenose dolphins with lobomycosis." (PMID 31481952, 2019).
lobular carcinoma (2 papers, 2012 to 2021). "For 480 ductal and for 72 lobular carcinoma samples FOXP3+/CD4+ cell ratios and overall survival data were available." (PMID 22471961, 2012). "Increased numbers of total CD4+ and FOXP3+ TIL were observed in ductal, as compared with lobular carcinomas." (PMID 22471961, 2012).
lung lymphoma (2 papers, 2025 to 2026). A rare non-Hodgkin or Hodgkin lymphoma that arises in and is confined to the lung at the time of diagnosis. "Bronchoalveolar lavage (BAL) flow cytometry demonstrated an aberrant CD4-predominant T-cell population (CD4:CD8 ratio 9.2:1) with loss of pan-T cell antigens CD5 and CD7, providing early evidence of pulmonary lymphoma involvement and prompting expedited hematological evaluation." (PMID 42212304, 2026).
lymphocytic leukemia (2 papers, 2014 to 2024). "In lymphocytic leukemia cell lines, these alterations result in changes in tumor infiltration of NK cells, macrophages, CD4+ T cells, and CD8+ T cells, and increased CD69 expression on both CD4+ and CD8+ T cells." (PMID 39436703, 2024). "The CD4+ T-cell model will hopefully be able to provide insight to for both T-cell biology (as demonstrated herein) as well as possible targets for lymphocytic leukemia treatments." (PMID 25538703, 2014).